DDR2 (discoidin domain receptor tyrosine kinase 2)
Description:
Tyrosine kinase involved in the regulation of tissues remodeling. It functions as a cell surface receptor for fibrillar collagen and regulates cell differentiation, remodeling of the extracellular matrix, cell migration and cell proliferation. Required for normal bone development. Regulates osteoblast differentiation and chondrocyte maturation via a signaling pathway that involves MAP kinases and leads to the activation of the transcription factor RUNX2. Regulates remodeling of the extracellular matrix by up-regulation of the collagenases MMP1, MMP2 and MMP13, and thereby facilitates cell migration and tumor cell invasion. Promotes fibroblast migration and proliferation, and thereby contributes to cutaneous wound healing.
Synonyms: NTRKR3; TKT; TYRO10; DDR2-N; MIG20a; WRCN
Tractability: Small molecule: an approved drug acts on it; a structure with a bound ligand is known; a high-quality ligand is known; it belongs to a druggable protein family. Antibody: UniProt places it where antibodies can reach, with high confidence; its Gene Ontology location is reachable by antibodies, with high confidence; UniProt predicts a signal peptide or a membrane-spanning region. PROTAC: it is named in the literature on targeted protein degradation; a small molecule that binds it is known.
Target class: Protein Kinase; Enzyme; Kinase; Tyrosine protein kinase DDR family; TK protein kinase group
Chemical probes: ALW-II-49-7 (high quality), BAY-826 (high quality), D2202-1 (high quality), SR-302 (high quality)
Gene: Protein-coding gene on chromosome 1 (162,630,863 to 162,787,405, forward strand). Ensembl gene ENSG00000162733.
Subcellular location: Cell membrane
Subcellular location (Human Protein Atlas): Actin filaments; Plasma membrane
Pathways (Reactome):
Extracellular matrix organization: Non-integrin membrane-ECM interactions
Gene Ontology:
Molecular function: collagen binding; protein binding; protein tyrosine kinase collagen receptor activity; transmembrane receptor protein tyrosine kinase activity; ATP binding; protein kinase activity; protein tyrosine kinase activity
Biological process: collagen-activated tyrosine kinase receptor signaling pathway; peptidyl-tyrosine phosphorylation; positive regulation of osteoblast differentiation; positive regulation of protein kinase activity; protein autophosphorylation; regulation of bone mineralization; regulation of tissue remodeling; biomineral tissue development; cell adhesion; cell surface receptor protein tyrosine kinase signaling pathway; chondrocyte proliferation; collagen fibril organization; endochondral bone growth; positive regulation of extracellular matrix disassembly; positive regulation of fibroblast migration; positive regulation of fibroblast proliferation; positive regulation of neuron projection development; positive regulation of phosphatidylinositol 3-kinase/protein kinase B signal transduction; regulation of extracellular matrix disassembly; signal transduction; cellular response to angiotensin; cellular response to hypoxia; cellular response to transforming growth factor beta stimulus; negative regulation of apoptotic process; negative regulation of hydrogen peroxide-mediated programmed cell death; and 9 more
Cellular component: focal adhesion; plasma membrane; receptor complex; apical plasma membrane; membrane
Genetic constraint (gnomAD): Loss-of-function variants: 27 observed, 99.31 expected, observed/expected ratio (o/e) 0.27, 90% interval 0.2 to 0.38. The upper end of that interval is the gene's LOEUF score, 0.38, which puts it in group 1 of 6, group 1 being the genes least tolerant of losing a copy. Missense variants: 783 observed, 1,136.7 expected, observed/expected ratio (o/e) 0.69, 90% interval 0.65 to 0.73. Synonymous variants: 382 observed, 398.75 expected, observed/expected ratio (o/e) 0.96, 90% interval 0.88 to 1.04.
Gene-disease validity (ClinGen):
ClinGen rates the evidence that DDR2 causes each of these diseases.
spondyloepimetaphyseal dysplasia-short limb-abnormal calcification syndrome (autosomal recessive): Definitive.
warburg-cinotti syndrome (autosomal dominant): Moderate. An autosomal dominant disease characterized by progressive corneal neovascularization, keloid formation, chronic skin ulcers, wasting of subcutaneous tissue, flexion contractures of the fingers, and acro-osteolysis.
Cancer hallmarks: invasion and metastasis (promotes)
Homologues: Orthologues: chimpanzee DDR2 (99% identical), macaque DDR2 (99% identical), pig DDR2 (98% identical), dog DDR2 (97% identical), guinea pig DDR2 (96% identical), mouse Ddr2 (96% identical), rat Ddr2 (95% identical), rabbit DDR2 (88% identical), tropical clawed frog ddr2 (82% identical), zebrafish ddr2a (77% identical), zebrafish ddr2b (66% identical). Paralogues in human: DDR1 (55% identical), INSR (20% identical), ROS1 (20% identical), FLT4 (20% identical), TIE1 (20% identical), IGF1R (20% identical), PDGFRB (20% identical), FLT1 (20% identical), NTRK3 (20% identical), FGFR2 (19% identical), KIT (19% identical), NTRK2 (19% identical), and 41 more.
Diseases named in the same sentence as DDR2 in open-access papers:
DDR2 is named in the same sentence as 128 diseases in open-access papers, as found by Europe PMC text mining. Sharing a sentence is not in itself a finding about the gene and the disease. The quoted sentences say what the papers report.
breast carcinoma (60 papers, 2014 to 2026). "Targeted suppression of DDR2 prevents TA-MSCs from promoting the growth and metastasis of breast cancer cells, possibly due to the loss of the mesenchymal phenotype and downregulation of genes related to tumorigenesis in TA-MSCs." (PMID 40676710, 2025). "DDR2, on the other hand, has been linked to higher tumor grade and shorter survival in breast cancer, as well as metastasis in gastric cancer, advanced staging in head and neck cancers, and increased risk of metastasis in ovarian cancer." (PMID 40563472, 2025). "DDR2 status was significantly associated with shorter disease-free survival (p = 0.0013) and shorter breast cancer-specific survival (p = 0.034)." (PMID 39766183, 2024). "We next analyzed the association between DDR2 or collagen type I status and clinical outcomes of breast cancer patients." (PMID 39766183, 2024). "It has been proposed that the DDR2/collagen axis promotes EMT in human cancers including breast cancer, while EMT is well known to be associated with the chemoresistance of breast cancer." (PMID 39766183, 2024). "Since we observed a significant association between DDR2/collagen type I and the proliferative ability of breast cancer in immunohistochemical analysis, we performed the cell proliferation assay using human breast cancer cell lines." (PMID 39766183, 2024). "Of importance, DDR2 immunoreactivity was positively associated with the aggressive behavior of breast cancers such as a higher invasion ability (pT) and cell proliferation (Ki67), especially in the collagen type I-positive group." (PMID 39766183, 2024). "Our recent prognosis analysis revealed that DDR2 immunoreactivity was associated with adverse clinical outcomes in breast cancer, like the previous report." (PMID 39766183, 2024). "Up-regulation of the discoidin domain receptor 2 (DDR2) elicits the susceptibility of ferroptosis by GSH consumption of recurrent breast cancer through the Hippo pathway." (PMID 36467032, 2022). "Deregulation of DDR2 expression and/or signalling has been associated with a wide variety of cancers including lung cancer, breast cancer, lymphoma and leukaemia." (PMID 35406381, 2022). "It has been shown in breast cancer that DDR2 expression is associated with hypoxia marker HIF-1α expression, with DDR2 expression and phosphorylation increased under intra-tumoral hypoxic conditions." (PMID 34805157, 2021). "An association between DDR2 and Snail1 has been revealed in several studies on breast cancer, ovarian cancer, papillary thyroid carcinoma, and hepatocellular carcinoma via different signaling pathways." (PMID 33917302, 2021). "We chose to focus on female mice in the current study to provide a baseline for future work examining the role of myeloid-derived CD45+DDR2+ cells in obesity-associated breast cancer." (PMID 31015794, 2019). "We performed second-harmonic generation microscopy for the analysis of collagen, defined tumor-associated collagen signature (TACS), the rate of mammary tumors, and the status of the collagen-DDR2-Snail axis of metastasis." (PMID 31046834, 2019). "An increased expression and activation of DDR2 in breast cancer cells are associated with a malignant phenotype and the expression of DDR2 is increased as a result of hypoxia." (PMID 26788073, 2016). "In an invasive carcinoma of breast cancer, high DDR2 expression is significantly associated with a high tumor grade and triple-negative subtype and worse survival." (PMID 27793038, 2016). "Our results are consistent with previous findings on breast cancer, suggesting the type I collagen can cause DDR2 phosphorylation and induce DDR2/ERK2/SNAIL1 signaling axis hyperactivation." (PMID 26362312, 2015). "Furthermore, the selective inhibition of DDR2 effectively hinders breast cancer metastasis-associated TA-MSCs from depositing collagen type I, thereby reducing their capacity to facilitate breast cancer progression." (PMID 40676710, 2025).
breast carcinoma (continued). "It is therefore reasonably hypothesized that DDR2 and increased collagen deposition is associated with the acquired chemoresistance of breast cancer." (PMID 39766183, 2024). "However, the contribution to the chemoresistance of DDR2 in terms of the association with collagens remains largely unclear in breast cancer." (PMID 39766183, 2024). "In addition, EMT-driven Discoidin Domain Receptor Tyrosine Kinase 2 (DDR2) upregulation stimulated ferroptosis susceptibility in recurrent breast cancer through the Hippo pathway." (PMID 36591279, 2022). "Indeed, immunohistochemistry on breast cancer tissues revealed an association of DDR2 expression with nuclear localization of Snail1, as well as with a loss of E-cadherin expression." (PMID 33917302, 2021). "In the breast cancer stroma, the action of DDR2 in cancer associated fibroblasts (CAFs) is particularly important for force-mediated remodeling of collagen fibers in the tumor extracellular matrix (ECM), thereby controlling the mechanical properties (e.g. stiffness) of the breast tumor stroma." (PMID 34477203, 2021). "The fibrillar collagen receptor tyrosine kinase (RTK) discoidin domain receptor 2 (DDR2) is essential for breast cancer metastasis in mouse models, and high expression of DDR2 in tumor and tumor stromal cells is strongly associated with poorer clinical outcomes." (PMID 34477203, 2021). "DDR2 in cancer-associated fibroblasts was reported to influence tumor cell invasiveness by way of paracrine mechanisms, extracellular matrix production and remodeling, studied in breast cancer." (PMID 27793038, 2016). "Moreover, DDR2 expression appears to be significantly associated with breast cancer lymph node metastasis." (PMID 25955408, 2015). "In breast cancer, activated DDR2 stabilizes SNAIL1, sustaining MT1-MMP production and activity and collagen synthesis, both of which contribute to the remodeling of collagen fibers at the tumour/ECM interface." (PMID 41492134, 2026). "In breast cancer, DDR2 acts as regulator of integrin-mediated mechano-transduction within the primary tumor." (PMID 41492134, 2026). "Collagen receptor discoidin domain receptor 2 (DDR2) facilitates metastatic site-TA-MSCs in enhancing breast cancer cells migration, invasion and collagen deposition." (PMID 40676710, 2025). "In the presence of collagen, DDR2 was found to increase tumor cell viability, emphasizing the importance of tumor responsiveness to the adjacent matrix in breast cancer progression." (PMID 39716322, 2024). "We first immunolocalized DDR2 and collagen type I in 224 breast cancer specimens, and the immunoreactivity of DDR2 was observed in the cytoplasm of the carcinoma cells, while it was quite slight in normal breast epithelium." (PMID 39766183, 2024). "Since chemotherapy often induces the apoptosis of breast cancer cells, we examined the effect of DDR2 on the apoptosis of breast cancer cells." (PMID 39766183, 2024). "Inhibiting DDR2 has been shown to decrease the migration of melanoma, fibroblasts, breast cancer, and lung cancer." (PMID 39459560, 2024). "Here, we demonstrated the involvement of the DDR2/collagen type I axis in breast cancer progression and chemoresistance." (PMID 39766183, 2024). "In the context of breast cancer recurrence, DDR2 expression has been demonstrated to be elevated in recurrent breast cancers compared to non-recurrent cases." (PMID 39716322, 2024). "On the contrary, DDR2 inhibitor WRG-28 suppressed the cell proliferation of EPI-resistant breast cancer cell lines (M-EPIR and 231-EPIR), in which DDR2 expression was significantly increased compared to parental cell lines." (PMID 39766183, 2024). "The following multivariate analysis revealed that DDR2 status (p = 0.0095) was identified as an independent prognostic factor for the recurrence of breast cancer along with pT (p = 0.012) and Ki67 LI (p = 0.031)." (PMID 39766183, 2024).
breast carcinoma (continued). "Although the mechanisms of aberrant DDR2 expression in breast cancer are yet to be fully elucidated, epithelial–mesenchymal transition (EMT)-associated transcription factors such as TWIST and SNAIL are reported to induce DDR2 in breast cancer." (PMID 39766183, 2024). "It has been also interestingly reported that DDR2 regulates the stiffness of breast cancer tissues via collagen type I reorganization to induce lung metastasis." (PMID 39766183, 2024). "We demonstrated in the present study that DDR2 contributes to breast cancer chemoresistance cooperatively with collagen type I and serves as a potent prognostic factor in breast cancer patients receiving chemotherapy." (PMID 39766183, 2024). "Collagen type I is a representative fibrillar collagen highly deposited in human malignancies including breast cancer and transduces protumor signals in breast cancer cells via its receptors such as DDR2." (PMID 39766183, 2024). "Various studies have demonstrated that DDR2 regulates cellular proliferation in embryonic cells, breast cancer cells, endochondral cells, and squamous cells." (PMID 39459560, 2024). "Although generally less studied in breast cancer, collagen type X is understood to promote invasion in other cancer types through binding of DDR2 and has become increasingly acknowledged for its role in breast cancer progression." (PMID 39716322, 2024). "DDR2 immunoreactivity was more frequently observed in the breast cancer tissues following neoadjuvant chemotherapy (p = 0.010)." (PMID 39766183, 2024). "Specifically, DDR2, a force signal receptor, was found to regulate the cell cycle arrest of breast cancer cells through the upregulation of STAT1/p27 signaling." (PMID 37369642, 2023). "It is known that the increase in the endogenous DDR2 mRNA in CAFs switches them into an active state and regulates “fibroblast-to-epithelial” transition during breast cancer development and progression." (PMID 36768815, 2023). "The receptor for collagen I, discoidin domain receptor tyrosine kinase 2 (DDR2), is upregulated in human mesenchymal breast cancer cells and ferroptosis-sensitive recurrent tumor cells." (PMID 38072908, 2023). "In support of this, we observed that DDR2 expression was robustly correlated with 42-gene mesenchymal metabolic signature across TCGA breast cancer samples (R = 0.84, Spearman)." (PMID 36713812, 2022). "Epithelial mesenchymal transition-driven upregulation of DDR2 suppresses tumor proliferation in recurrent breast cancer by regulating YAP/TAZ-mediated ferroptosis." (PMID 36467032, 2022). "Consistent with selective DDR2 mesenchymal expression, DDR2 is upregulated by the epithelial-to-mesenchymal inducing transcription factor TWIST1 in breast cancer cells." (PMID 36249782, 2022). "Consistent with this, a major role of CAF‐derived DDR2 in collagen fiber organization and breast cancer metastasis has been reported." (PMID 34957688, 2022). "We next utilized TCGA and METABRIC breast cancer datasets to explore the correlation of DDR2 with other components of the shared FOXQ1-SNAIL gene set." (PMID 36713812, 2022). "Because DDR2 has been repeatedly found to drive metastasis in multiple cancer types, including breast cancer, we examined DDR2 expression in a set of mouse breast cancer cell lines that demonstrated differential metastatic capabilities in vivo." (PMID 36713812, 2022). "In a prior study to decipher the role of DDR2 signaling in CAFs on tumor lung colonization in a breast cancer model, it was observed that CAFs co-injected with tumor cells into mice survived for less than 7 days." (PMID 35884543, 2022). "Specifically, DDR2 was highly expressed in five basal-like breast cancer cell lines, including BT549, Hs." (PMID 36713812, 2022). "In a preliminary analysis of the correlation of DDR2 expression and 42-mesenchymal metabolism enzymes across TCGA breast cancer samples, we found a robust positive correlation (R = 0.84, Spearman)." (PMID 36713812, 2022).